ENSG00000287458 (novel transcript, antisense to FKBP5)
Gene: Long non-coding RNA gene on chromosome 6 (35,650,997 to 35,652,856, forward strand). Ensembl gene ENSG00000287458.
Gene Ontology:
Biological process: RNA processing
Cellular component: nucleolus